NLRP3 (NLR family pyrin domain containing 3)
Diseases named in the same sentence as NLRP3 in open-access papers (continued):
Sharing a sentence is not in itself a finding about the gene and the disease.
COVID-19 (continued). "Anakinra is also used to treat COVID-19 because the macrophage NLRP3 inflammasome is activated and IL-1β production is promoted." (PMID 35464987, 2022). "Analyses of PBMCs from COVID-19 patients incubated with the NLRP3 trigger nigericin revealed that the activation potential of the NLRP3 inflammasome varies across myeloid cell subsets and COVID-19 severity." (PMID 36209522, 2022). "The involvement of NLRP3-inflammasome in COVID-19 is confirmed by SARS-CoV-2 N protein possibility to directly interact with NLRP3, thus promoting the inflammasome activation." (PMID 35336077, 2022). "Consistently, our data of NLRP3 showed a positive correlation with IL-1β, as suggested by previous studies where NLRP3 role in COVID-19 is highlighted." (PMID 35812405, 2022). "Firstly, active NLRP3 inflammasome and caspase-1 are detected in the peripheral blood and tissues of COVID-19 patients and are positively correlated with severity markers for COVID-19 (e.g., IL-6)." (PMID 36532040, 2022). "The results indicate that COVID-19 exosomes transcriptionally induce NLRP3 inflammasome components in endothelial cells of two different anatomical sources." (PMID 35587188, 2022). "Freeman and Swartz reviewed the literature on pathogenesis of NLRP3 activation and severe COVID-19, concluding the necessity of investigation into NLRP3 inflammasome as a therapeutic target." (PMID 36618363, 2022). "Clinical benefits of statins in COVID-19 patients were raised based on their anti-inflammatory effects, particularly on NF-kB and NLRP3." (PMID 35966209, 2022). "This suggests a role of the NLRP3 inflammasome in the pathophysiology of the disease, as a marker of disease severity and a potential therapeutic target for COVID-19." (PMID 36105941, 2022). "Herein, the present review article combines the simultaneous detrimental effects of mitochondrial dysfunction, autophagy, NOX, NO, ROS, NLRP3, and TLRs during COVID-19." (PMID 35639261, 2022). "Targeting overactivation of the Ang II-AT1R axis represents another strategy to attenuate NLRP3 inflammasome activation and cell pyroptosis in COVID-19." (PMID 35697684, 2022). "Our results revealed that exosomes from severe COVID-19 patients trigger (i) NLRP3, caspase-1, and IL-1β transcription; (ii) NLRP3 inflammasome activation; and (iii) maturation and secretion of IL-1β from endothelial cells." (PMID 35587188, 2022). "We observed that the serum level of NLRP3 inflammasome was significantly increased in COVID-19 patients with headache." (PMID 34384355, 2021). "This study also confirmed the anti-inflammatory effects of quercetin besides its therapeutic potential in diseases with inflammatory background and NLRP3 inflammasome activity, which is a known factor in the immunopathogenesis of COVID-19." (PMID 33509217, 2021). "Statins restrict the “cytokine storm” in patients with severe COVID-19 by blocking the NF-κB pathway and NLRP3 inflammasomes to exert their anti-inflammatory properties and by reducing the invasion of viruses to destroy lipid rafts." (PMID 34504502, 2021). "The higher levels of Caspase-1 p20 and IL-18 indicated more severe symptoms and worse prognosis in patients with COVID-19, suggesting that NLRP3 inflammasome is not only activated but also plays a key role in COVID-19 progression." (PMID 34150848, 2021). "The coronavirus tolerance observed in bats has been associated to a dampened transcriptional priming of NLRP3, which confirms that targeting the NLRP3/IL-1β pathway is a successful strategy in COVID-19." (PMID 33916409, 2021). "A phenomenon observed in COVID-19 patients is NLRP3-inflammasome activation leading to the overproduction of IL-18, which is similar to that observed in AOSD." (PMID 34948117, 2021). "Growing evidence has shown that colchicine inhibits NLRP3 inflammasome activation and effectively reduces the overall mortality of COVID-19 patients." (PMID 34150848, 2021).
COVID-19 (continued). "In cardiac complicated COVID-19 patients, the molecular role of intracellular molecule inflammasome NLRP3 is well described." (PMID 34604534, 2021). "In light with this, molecular factors that affect the overactivation of NLRP3 inflammasome are vital for predicting the outcome of COVID-19 patients." (PMID 34150848, 2021). "Activation of the NLRP3 inflammasome by SARS-CoV-2 was observed in lung tissues of patients with COVID-19." (PMID 34051877, 2021). "In this review, we will propose a possible mechanism by which H2 inhibits NLRP3 activation via the inhibition of mitochondrial oxidation and then present a perspective on the potential effects of H2 on chronic inflammatory diseases including coronavirus disease 2019 (COVID-19)." (PMID 33806292, 2021). "At least for SARS-CoV-2 we were able to show that primary human macrophages derived from COVID-19 patients also activate the NLRP3 inflammasome upon spike protein exposure." (PMID 34696506, 2021). "Moderate and severe COVID-19 patients showed enhanced NLRP3 activation in PBMCs and lungs, which positively correlated with the severity of disease." (PMID 34439920, 2021). "They found active NLRP3 inflammasome in peripheral blood mononuclear cells (PBMCs) and tissues of postmortem patients upon autopsy in patients with COVID-19." (PMID 33806292, 2021). "We next sought to investigate the crosstalk between the oxidative stress pathway and NLRP3-caspase-1 activation on circulating blood monocytes during COVID-19." (PMID 35095880, 2021). "Studying moderate and severe COVID-19 patients Rodrigues and co-workers found active NLRP3 inflammasome in peripheral blood mononuclear cells and tissues of postmortem patients upon autopsy." (PMID 34960782, 2021). "More evidence is required, however, to recognize the NLRP3 inflammasome activation pathway as a potential therapeutic target for the treatment of cerebrovascular disorders in COVID-19." (PMID 33923537, 2021). "The next few years will be crucial for identifying potential early indicators of neurodegeneration in patients who have survived COVID-19 and to finally elucidate the physiological and pathological role of Aβ and the NLRP3 inflammasome." (PMID 34209586, 2021). "Recently, the dysregulated NLRP3 inflammasome activation that releases nociceptive cytokines is proposed in COVID-19 headache pathophysiology." (PMID 34384355, 2021). "We next tested the effect of MCC950, a specific inhibitor of the NLRP3 inflammasome, and colchicine, an anti-inflammatory compound, on spontaneous cytokine release from COVID-19 patient cells." (PMID 35095880, 2021). "Nevertheless, our results indicate NLRP3 as the main inflammasome sensor promoting the poor outcome of COVID-19, in agreement with other reports." (PMID 35095880, 2021). "These therapeutic options are shown to limit the NLRP3 activation, and the release of IL-1β—one of the proinflammatory cytokines detected during COVID-19 progression." (PMID 33923537, 2021). "For example, severe acute respiratory syndrome coronavirus-2 (SARS-CoV-2) infection triggers the NLRP3 inflammasome in COVID-19 patients." (PMID 35062226, 2021). "The previous studies and clinical evidence also strongly indicate the importance of the NLR family pyrin domain containing 3 (NLPR3) inflammasome in the pathologic effects of severe COVID-19." (PMID 33643932, 2021). "Recent data suggest early activation of the NLRP3 inflammasome in severe COVID-19; the formation of the end product caspase-1 was enhanced among patients who had unfavorable outcome." (PMID 33682678, 2021). "It has been proposed that the enhanced lethality of COVID-19 in older patients is a result of age-related hyperactivation of the NLRP3 inflammasome." (PMID 34203190, 2021). "NLR family pyrin domain containing 3 (NLRP3) inflammasome activation was also shown to contribute to the exacerbated inflammatory response in COVID-19 patients." (PMID 33613573, 2021).
COVID-19 (continued). "Apart from colchicine and hydroxychloroquine, there are also other new or classic drugs that inhibit NLRP3 inflammasome and potentially effective to prevent the cytokine storms in COVID-19 patients, including Tranilast and Oridonin." (PMID 34150848, 2021). "In humans, effective suppression of the NLRP3/IL-1 axis by BTK inhibitors, and thus a positive regulatory effect of BTK on NLRP3, was instead suggested by a recent off-label trial of acalabrutinib in COVID-19 patients." (PMID 33718366, 2021). "NLRP3 was correlated with headache duration (w = 0.69) and hospital stay (w = 0.63) in COVID-19 patients with headache." (PMID 34384355, 2021). "PBMCs from patients with COVID-19 exhibit active intracellular caspase-1, increased expressions of NLRP3 and ASC, and the secretion of IL-1β." (PMID 34360684, 2021). "Our findings provide insights into the pathogenesis of COVID-19, both during acute infection and early recovery, suggesting inhibition of both NLRP3 activation and lipid peroxidation as potential therapeutic interventions in COVID-19." (PMID 35095880, 2021). "Excess activation of NLRP3 inflammasome increases the cardiovascular complication in COVID-19 patients." (PMID 34512335, 2021). "Studies have shown that SARS-CoV-2 elevated inflammation and activates NLRP3 inflammasome, this leads to a cytokine storm and destructive inflammation and Causes ALI/ARDS in patients with COVID-19." (PMID 33509217, 2021). "The SARS-CoV-2 S protein was recently shown to prime inflammasome formation and drive NLRP3 inflammasome activation in macrophages derived from patients with COVID-19." (PMID 34360684, 2021). "Although COVID-19 pathogenesis remains elusive, emerging evidence indicates the role of NLRP3 inflammasome involvement in its pathogenesis." (PMID 34835501, 2021). "The NLRP3 is activated through the oxidized LDL and TNF α, causing cytokine storms and cardiac complications in COVID-19 patients." (PMID 34604534, 2021). "Collectively, our findings suggest oxidative stress/NLRP3 signaling pathway as a potential target for host-directed therapy to mitigate early COVID-19 hyperinflammation and also its long-term outcomes." (PMID 35095880, 2021). "In this review, we aim to investigate the impact PB have on stimulating the assembly of NLRP3 inflammasome, as well as the pathophysiological mechanisms supporting the use of PB in COVID-19." (PMID 34835501, 2021). "Growing evidence suggests that NLRP3 inflammasome activation in macrophages and lung epithelial cells is involved in the development of pneumonia in patients with COVID-19." (PMID 34684771, 2021). "Compared to the CONTROL group, increased mRNA transcription was observed for TLRs 3, 7, 9, RIGI, and NLRP3 in the entire COVID-19 group, while TLR8 was decreased." (PMID 34315957, 2021). "Compared with other coronavirus infections, the mortality of COVID-19 caused by SARS-CoV-2 is relatively lower, indicating a moderate activation of NLRP3 inflammasome in COVID-19 patients." (PMID 34150848, 2021). "Our data show for the first time that um-PEA, via PPAR-α, markedly inhibits the SP induced NLRP3 signalling pathway outlining a novel mechanism of action of this lipid against COVID-19." (PMID 34564408, 2021). "A study on the role of inflammasomes in COVID-19 examined NLRP3 in human peripheral blood mononuclear cells and tissues of postmortem patients." (PMID 34123871, 2021). "In the blood, the classical and lectin-induced complement pathways, as well as the NLRP3 inflammasome, plasma cells (PCs), and monocytes (Mo) were significantly enriched in COVID-19 patients, whereas cytotoxic cells and neutrophils were decreased." (PMID 33782412, 2021). "Melatonin was also recognized as a relevant modulator of innate and adaptive immune reactions and specifically of the inflammasome NLRP3, the latter being a hyperactivated pathway in COVID-19 patients, contributing to the so-called “cytokine storm”." (PMID 33921297, 2021).
COVID-19 (continued). "Post-mortem lung tissues from patients with COVID-19 exhibit enormously increased numbers of NLRP3 and ASC-positive cells compared to those of control lung tissues." (PMID 34360684, 2021). "Further studies are warranted to validate the role of NLRP3 in clinical outcomes of COVID-19 and the biological mechanisms involved in the inflammatory response to infection." (PMID 33923537, 2021). "The first clinical study of an NLRP3 inflammasome inhibitor (tranilast) to treat COVID-19 is ongoing in China." (PMID 33553222, 2020). "Future research should also evaluate changes in EC redox status after COVID-19 recovery, potentially through analysis of oxidative stress biomarkers and redox-sensitive proteins like p90RSK and NLRP3." (PMID 33519510, 2020). "An anti-allergic drug which inhibits NOD-, LRR- and pyrin domain-containing protein 3 (NLRP3) which plays an important role in the pathogenesis of COVID-19." (PMID 32754159, 2020). "Considering that NLRP3 is frequently over-activated in elderly individuals, it is believed that the NLRP3 inflammasome plays a central role in the increased lethality observed in aged COVID-19 patients." (PMID 33584335, 2020). "Cross-regulation between type I interferon (IFN-I) and the NLRP3 inflammasome is implicated in the abrupt proinflammatory response to immunosuppressive switch characteristic of SARS and COVID-19 ARDS through an undefined mechanism." (PMID 32655582, 2020). "Patients with a reduced immune fitness can demonstrate a dysregulated NLRP3 inflammasome activity resulting in severe COVID-19 with tissue damage and a cytokine storm." (PMID 32670297, 2020). "In our opinion, the NLRP3 inflammasome plays a central role in the increased lethality observed in elderly patients infected by COVID-19." (PMID 32765942, 2020). "The rapid decline of COVID-19 patients coincides with an abrupt shift from the NLRP3 cytokine storm to a compensatory immunosuppressive state." (PMID 32655582, 2020). "In older individuals over 65, a decrease in NAD+ levels reduces the activity of SIRT2, leading to hyperactivation of NLRP3 and increased cytokine storms found in older COVID-19 patients." (PMID 33426541, 2020). "The data presented in this overview suggest that the NLRP3 inflammasome with its downstream pathways is an attractive target for therapy of COVID-19 with (severe) pathology in individuals that have a low immune fitness." (PMID 32670297, 2020). "In COVID-19, dysregulation of the NLRP3 inflammasome in monocytes and macrophages seems to be involved in a hyperinflammatory state contributing to severe tissue damage." (PMID 33553222, 2020). "The potential central role of NLRP3 in severe COVID-19 necessitates investigation into the therapeutic targeting of the NLRP3 inflammasome." (PMID 32655582, 2020). "Here we review the literature that describes the pathogenesis of severe COVID-19 and NLRP3 activation and describe an important role in targeting this pathway for the treatment of severe COVID-19." (PMID 32655582, 2020). "IL-1ra circulates in much higher levels than IL-1 itself, is involved in NLRP3 inflammasome activation and has been suggested as a reliable marker of IL-1 activity in COVID-19 disease." (PMID 33303843, 2020). "COVID-19 severity has been correlated with NLRP3 inflammasome activation." (PMID 40406515, 2025). "Inhibiting the NLRP3 inflammasome may reduce hyperinflammation and lung injury in COVID-19 patients, as well as in experimental mouse models." (PMID 40508226, 2025). "SARS-CoV-2 nucleocapsid (N) promotes NOD-like receptor protein 3 (NLRP3) inflammasome activation to induce hyperinflammation and severe symptoms of coronavirus disease-19 (COVID-19) by promoting the binding of NLRP3 with ASC and facilitating NLRP3 inflammasome assembly." (PMID 40253364, 2025). "NLRP3 inflammasome activation is strongly correlated with COVID-19 severity and part of dexamethasone’s clinical effect in COVID-19 may be via NLRP3 inhibition." (PMID 39882243, 2024).
COVID-19 (continued). "Indeed, NLRP3 inflammasome activation, which induces IL-1β, has been described in neutrophils from severe COVID-19 patients and this pathway seems to be particularly involved in older patients." (PMID 38715114, 2024). "While NLRP3 inflammasome activation serves as a catalyst for immune responses, its excessive activation may precipitate an exaggerated inflammatory response in COVID-19, potentially contributing to severe illness and complications." (PMID 38399989, 2024). "The association between the NLRP3 inflammasome pathway and disease severity markers were assessed in the presence and absence of VitD3 among severe COVID-19 patients." (PMID 38748756, 2024). "This suggests that COVID-19-induced activation of the NLRP3 pathway could accelerate the aging process by amplifying inflammation." (PMID 39720706, 2024). "However, we cannot exclude a role for this pathway earlier in the course of disease before MIS-C symptoms develop, since NLRP3 activation has been reported in symptomatic adult COVID-19 patients." (PMID 38762592, 2024). "Moreover, NLRP3 inflammasome products, such as IL-1β and IL-18, are increased in patients with severe acute COVID-19 and positively correlated with adverse clinical outcomes." (PMID 39012668, 2024). "This intersection between NLRP3 activation, COVID-19, and aging is crucial for understanding how long COVID may exacerbate immune aging." (PMID 39720706, 2024). "If this is the case, then proposed COVID-19 treatments, like Quercetin, an Nlrp3 inflammasome inhibitor, could treat acute COVID-19 infections by inhibiting the cytokine storm and, ultimately, prevent the formation of malignant processes." (PMID 39634968, 2024). "Furthermore, the involvement of the NLRP3 inflammasome is paramount in the pathogenesis of multi-organ damage induced by COVID-19." (PMID 38399989, 2024). "Both S and N proteins activate the NLRP3 inflammasome, which may explain an earlier finding that endothelial cells exposed to COVID-19 EVs exhibited activation of the NLRP3 inflammasome." (PMID 39475319, 2024). "Differential expression analysis and MR analysis showed that NLRP3 was positively associated with the risk of severe COVID-19 and involved 11 SNPs, of which rs4925547 was not significantly co-localized." (PMID 39385934, 2024). "Both the NLRP3 subunit and caspase 1 (assessed using an antibody that detects both pro-caspase and activated caspase) were found to be significantly increased in patients with COVID-19." (PMID 38771750, 2024). "Attenuating the NLRP3 inflammasome pathway by VitD3 was accompanied by a decrease in IL-1β, IL-6, IL-17, and D-dimer, reduced hyperinflammation of severely infected COVID-19 patients, as well as correlated with enhanced type I IFN signaling and reduced disease severity." (PMID 38748756, 2024). "Expressed in myeloid cells, the NLRP3 inflammasome is a component of the innate immune system and is involved in the activation of many inflammatory processes, including the generation of the COVID-19 cytokine storm." (PMID 39064010, 2024). "In this line, a recent study unveiled a spontaneous NLRP3 inflammasome over-activation and IL-1β secretion in monocytes from severe COVID-19 patients that could be reverted by treating the patients with the IL-1 receptors blocker anakinra." (PMID 38225643, 2024). "Activation of the NLRP3 inflammasome, which contributes to the severity of COVID-19 was studied in in vitro infected macrophages and monocytes, in mouse models, and in lung cells with severe COVID-19." (PMID 38974521, 2024). "The intricate relationship between the heightened production of interleukin-1 (IL-1) in severe COVID-19 cases and the activation of NLRP3 inflammatory bodies has prompted extensive exploration within the scientific community to devise novel treatment modalities." (PMID 38399989, 2024).